LINC01280 (long independently transcribed non-coding RNA 1280)
Gene: Long non-coding RNA gene on chromosome 2 (216,558,195 to 216,606,938, reverse strand). Ensembl gene ENSG00000224391.
Diseases named in the same sentence as LINC01280 in open-access papers:
LINC01280 is named in the same sentence as 2 diseases in open-access papers, as found by Europe PMC text mining. Sharing a sentence is not in itself a finding about the gene and the disease.
LINC01280 shares sentences with these, for which no sentence is quoted: cancer (1 paper); osteosarcoma (1).